IGF2 (insulin like growth factor 2)
Diseases named in the same sentence as IGF2 in open-access papers (continued):
Sharing a sentence is not in itself a finding about the gene and the disease.
lung cancer (continued). "For example, in various human cancers, including lung cancer, IGF2 can undergo loss of imprinting (LOI), causing the silenced maternal allele to reactivate and boost IGF2 expression." (PMID 38001653, 2023). "Animals that overexpress IGF2 are at an increased likelihood of developing mammary gland adenocarcinoma as well as lung cancer." (PMID 37393293, 2023). "In this study, chemotherapy-induced lung cancer cells excreted exosomes and transferred IGF-2 into BMSCs." (PMID 36568212, 2022). "Osimertinib-treated lung cancer patients were found to have increased IGF2 expression, and IGF2 autocrine-mediated IGF1R pathway activation is one of the causes of osimertinib resistance in lung cancer patients." (PMID 35684449, 2022). "Our study is the first to find IGF2 and RTCH1 mutations in peripheral blood CTC NGS of early lung cancer." (PMID 34136379, 2021). "For example, in lung cancer, IGF-2, which is regulated by miR-494, can facilitate the proliferation of A549 cells." (PMID 32399056, 2020). "The combined expression levels of H19 lncRNA and IGF2 driven by P4 promoter in lung cancer patients is higher than each one alone, so the use of this vector should substantially increase the therapeutic index." (PMID 25884481, 2015). "In the present study, the precise incidence of IGF2 LOI in lung carcinomas was examined using PCR-RFLP in combination with DNA sequencing of samples obtained by a laser capture microdissection (LCM) method." (PMID 25364428, 2014). "Here, we evaluated the effects of smoking, green tea consumption, and IGF1, IGF2, and IGFBP3 genotypes on lung cancer risk." (PMID 22347413, 2012). "Subsequently, we analyzed the joint effect of cumulative smoking dose with IGF1, IGF2, and IGFBP3 genotypes on lung cancer risk after adjusting for the effect of green tea consumption, exposure to cooking fumes, and family history of lung cancer." (PMID 22347413, 2012). "In this study, we evaluated the effects of smoking, green tea consumption, as well as IGF1, IGF2, and IGFBP3 polymorphisms, on lung cancer risk." (PMID 22347413, 2012). "Insulin-like growth factors (IGFs), IGF1 and IGF2 are peptide hormones with strong mitogenic effect on both normal and cancerous cells, including lung cancer." (PMID 22347413, 2012). "The joint effect of cumulative smoking dose with IGF1 (CA)n repeat, IGF2 820, IGFBP3 -202 genotypes for lung cancer risk." (PMID 22347413, 2012). "Regardless, heavy smoking in cumulative dose would likely increase lung cancer risk by increasing carcinogen exposure long-term, while simultaneously increasing IGF1 or IGF2 levels or decreasing IGFBP3 levels." (PMID 22347413, 2012). "The activation of IGF-IR facilitates malignant transformation and the majority of IGF-2 transgenic mice develop lung cancer by 18 months of age." (PMID 21464968, 2011). "Numerous studies have indicated that the levels of IGF-1 and IGF-2 are increased in the tumor tissues of lung cancer, and these growth factors promote cell growth, proliferation, invasion, and apoptosis suppression by activating multiple signaling pathway, including PI3K/Akt and Ras/MAPK." (PMID 40741172, 2025). "ITGA11 has been reported to enhance the tumorigenicity of lung cancer by modulating IGF-2." (PMID 40275351, 2025). "Given that lung cancer cells induced CAFs activation via IGF2 secretion, we wondered whether IGF2 could induce autophagy of NFs." (PMID 39759028, 2024). "While the exact mechanism(s) underlying the associated development of lung cancer and COPD are currently unknown, our data shed new light on the emerging concept that diseases are closely linked to IGF2-mediated signaling in AT2s." (PMID 38902841, 2024). "Given that 15–20% of emphysema and lung cancers worldwide are TS-related, NB activation of the IGF2-IGF-1R/IR signaling pathway may help us understand the pathogenesis underlying the development of these two deadly diseases in smokers." (PMID 38902841, 2024).
lung cancer (continued). "First, we compared the IGF2 level in lung cancer cells and fibroblasts." (PMID 39759028, 2024). "In order to demonstrate this hypothesis, neutralizing antibody against IGF2 was added to lung cancer cell-CM and to culture NFs." (PMID 39759028, 2024). "In summary, we demonstrated that lung cancer cells activated CAFs via IGF2-mediated autophagy induction and, in return, iCAFs stimulated lung cancer cell migration and invasion via CXCL12-mediated AKT/NF-κB pathway, indicating a positive feedback regulation between lung cancer cells and CAFs." (PMID 39759028, 2024). "There is minimal data on the mechanism of initiation of the LOI of IGF2 in lung cancers." (PMID 35974000, 2022). "We then examined whether FOXA1 binding affected the methylation status of the CTCF binding sites at ICR locus, which is critical to LOI of IGF2 in lung cancer." (PMID 35974000, 2022). "We do observe that FOXA1 expression help to maintain the phosphorylation status of IGF1R signaling cascade of lung cancer cells in the serum starvation conditions, which might be explained by increased IGF2 autocrine in lung cancer cells by FOXA1." (PMID 35974000, 2022). "CAFs also produce IGF2 that binds to the IGF1 receptor in lung cancer cells and activate the AKT/Sox2 pathway, leading to enhanced expression of P glycoprotein (PG-P), a member of the ATP-binding cassette transporters, that is capable of pumping out the chemotherapeutic drug." (PMID 33673405, 2021). "A recent study also showed that IGF1, the adult-type IGF sharing the same IGF axis signaling with IGF2, is responsible for the initiation of lung cancer recurrence by inducing self-renewal and clonal expansion of cancer stem cells and results in subsequent neoangiogenesis and recurrence." (PMID 34539876, 2021). "However, several studies showed that YAP promotes radioresistance and genomic instability in medulloblastoma through IGF2-mediated Akt activation, and conversely, its inhibition sensitizes lung cancer cells to radiation." (PMID 32850759, 2020). "Since ZFP57 regulates IGF2 expression, this axis may well be a potential target for lung cancer treatment." (PMID 31245293, 2019). "In the present study, the status of genomic imprinting of IGF2 in lung cancer was evaluated." (PMID 25364428, 2014). "Heavy smokers carrying susceptible IGF1, IGF2, and IGFBP3 have a higher risk of lung cancer." (PMID 22347413, 2012). "Thus, IGF2 LOI lung carcinoma appears to be a good candidate for molecular-targeted therapy." (PMID 25364428, 2014). "However, IGF1, IGF2, and IGFBP3 may be susceptibility genes for lung cancer only in certain ethnic populations." (PMID 22347413, 2012). "However, no significant decrease in risk of lung cancer was found for green tea drinkers with IGF2 and IGFBP3 genotypes (data not shown)." (PMID 22347413, 2012). "Hsa-miR-320b also inhibits lung cancer angiogenesis and tumor growth by inhibiting the hepatocyte nuclear factor 4 gamma (HNF4G) and insulin-like growth factor 2 mRNA-binding protein 2 (IGF2BP2) expression." (PMID 35958401, 2022). "Evidence of increased expression of insulin-like growth factor 2 (IGF2) and insulin-like growth factor receptor-1 (IGF-1R) in CAF accumulating-lung cancer tissues proved that CAFs promote chemoresistance through IGF2/IGF-1R signal." (PMID 34095111, 2021). "Other pathways that are involved in CAF-induced resistance of lung cancer cells to chemotherapy include the ANXA3/JNK, IGF2/AKT/Sox2/PG-P, and PI3K/Akt/GRP78 signaling pathways." (PMID 33673405, 2021). "IGF2-targeting strategies, including voltage-dependent calcium channel blocker (CCB) and a neutralizing antibody, significantly suppressed the NB-induced development of emphysema and lung cancer." (PMID 38902841, 2024).
lung cancer (continued). "Interestingly, the IGF axis is a complex molecular network (including peptide‐ligands IGF1, IGF2, and insulin, and the receptors IGF1R, IGF2R, and INSR) that is involved in a wide variety of neoplasms such as prostate, breast, colorectal, and lung cancers." (PMID 34668636, 2022). "However, CAFs survive single high dose and fractionated radiation doses and promote irradiated lung cancer cell recovery and tumor relapse after radiotherapy by CAF-derived IGF2-induced autophagy via mTOR suppression." (PMID 33673405, 2021). "In addition, it has also been shown that overexpression of IGF2 induces resistance to targeting agents, such as the EGFR inhibitors, osimertinib and erlotinib, by re-activating the AKT and MAPK pathways in lung cancer and cholangiocarcinoma." (PMID 34067117, 2021). "Lung cancer-specific cDMCs were found at the promoters of SH3GL3, IGF2, and TMEFF2." (PMID 28751909, 2017). "We also evaluated the effect of IGF1, IGF2, and IGFBP3 (data not shown) on lung cancer risk by green tea consumption." (PMID 22347413, 2012). "Additionally, repositioning calcium signaling-blocking drugs such as CCBs is a novel strategy for targeting IGF2 signaling to prevent both emphysema and lung cancer without the potential deleterious effects of metabolic disorders." (PMID 38902841, 2024). "However, persistent IGF2 overexpression during NB-induced severe injury results in hyperproliferation of AT2s without coordinated AT2-to-AT1 differentiation, disrupting alveolar repair, which leads to the concurrent development of emphysema and lung cancer." (PMID 38902841, 2024). "However, we did not observe an independent relationship between the IGF2 and IGFBP3 polymorphisms and risk of lung cancer." (PMID 22347413, 2012). "In keeping with this speculation, we observed that heavy smokers with susceptible IGF1, IGF2, and IGFBP3 genotypes had an elevated risk of lung cancer, although the interaction effect was not significant." (PMID 22347413, 2012).
Silver-Russell syndrome (58 papers, 2008 to 2026). Silver-Russell syndrome is characterized by growth retardation with antenatal onset, characteristic facies and limb asymmetry. "Rationale: Skeletal deformities are characteristic manifestations of Silver-Russell Syndrome with mutations in insulin-like growth factor 2 (IGF2) gene serving as the most prevalent genetic abnormality." (PMID 40384861, 2025). "SHORT syndrome has significant phenotypic overlap with Silver-Russell syndrome, an imprinting disorder associated with diminished IGF2 expression, which is considered as a differential diagnosis for SHORT syndrome." (PMID 40568952, 2025). "Their deregulated expression is the cause of Beckwith–Wiedemann syndrome (H19, IGF2, KCNQ1OT1), Russel-Silver syndrome (H19, IGF2, KCNQ1OT1) and Uniparental disomy 14 (MEG3) and is also observed in several tumors." (PMID 31143763, 2019). "Conversely, severe hypomethylation of the H19 DMR or IGF2 DMR on the paternal allele (associated with IGF2 repression) is found in over 50% of patients with Silver-Russell Syndrome, characterized by intrauterine and post-natal growth retardation." (PMID 24934635, 2014). "In addition, we found that imprinted genes in the H19/Igf2 cluster associated with Beckwith-Wiedemann and Silver-Russell syndromes (BWS & SRS) were dysregulated." (PMID 24818964, 2014). "Imprinting disorders, with hypomethylation of genetic control regions, may result in down-regulation of IGF2 expression by the paternal allele and are involved in short stature due to both pre-natal and post-natal growth failure in Silver-Russell syndrome and Temple syndrome." (PMID 31555216, 2019). "In contrast, loss of methylation (LOM) of the paternal allele at the same IC is associated with loss of paternal allele IGF2 expression and the phenotype of Silver-Russell syndrome (SRS), which is characterised by pre- and postnatal growth restriction." (PMID 24325814, 2013). "In Silver-Russell Syndrome (SRS) Hypomethylation of the H19/IGF2 imprinted domain on chromosome 11p15 accounts for 50–60% of cases of Silver-Russell Syndrome (SRS), while maternal uniparental disomy of chromosome 7 (MatUPD7) is found in about 10% of cases." (PMID 40730975, 2025). "Rearrangement of HMGA2 is suggested to drive tumorigenesis by the (dis-)regulatory effect of the HMGA2 protein on PLAG1 and IGF2 expression, a suggestion based on the downregulation of IGF2 expression in patients with Silver-Russel syndrome." (PMID 40338436, 2025). "A mouse study found cases in which fetal IGF2 is misregulated (Beckwith-Wiedemann and Silver-Russell syndromes) can be diagnosed, and growth can be rescued by prenatally adjusting IGF2 or its signaling pathway." (PMID 37152930, 2023). "In humans, the loss of PLAGL1 expression causes ‘transient neonatal diabetes mellitus’ (TNDM, OMIM 601410), an imprinting disorder characterised by intra-uterine growth restriction, similarly to what is observed in Silver-Russell Syndrome (SRS), an ID most often caused by reduced IGF2 expression." (PMID 37686455, 2023). "In most patients with Silver-Russel-syndrome there is a hypomethylation of the imprinting cluster region on the paternal chromosome 11p15.5, which leads to biallelic silencing of the IGF2-gene and a biallelic expression of the noncoding region H19." (PMID 36440208, 2022). "The role of IGF-2 in fetal growth has been demonstrated in the context of the Silver-Russel syndrome, characterized by extreme intrauterine growth restriction due to disorders in the methylation pattern of the IGF-2 gene in affected fetuses." (PMID 36440208, 2022). "IGF2, as well as the H19 gene, when hypomethylated at the ICR1 locus, are associated with Silver-Russell syndrome." (PMID 34356068, 2021). "The imprinting disorder Silver-Russell syndrome (SRS) is a clinically and genetically heterogeneous condition characterized by severe intrauterine and postnatal growth retardation caused by reduction of insulin-like growth factor 2 (Igf2) gene expression." (PMID 32234052, 2020).
Silver-Russell syndrome (continued). "The IGF2 locus is used in clinical diagnostic settings to identify Beckwith-Wiedemann syndrome, which is characterized by overgrowth, and the H19 locus has been used in the diagnosis of Silver-Russell syndrome (SRS), which is characterized by undergrowth." (PMID 29988473, 2018). "Loss of paternal methylation (LOM) of the H19/IGF2 intergenic differentially methylated region (H19/IGF2:IG-DMR) causes alteration of H19/IGF2 imprinting and Silver-Russell syndrome (SRS)." (PMID 29484033, 2018). "The in vitro analysis of the hypomethylation of imprinting control region 1 (ICR1) within the IGF2/H19 locus is challenged by the mosaic distribution of the epimutation in tissues from children with Silver-Russell syndrome (SRS)." (PMID 25657826, 2015). "H19/IGF2 with copy number variations, located on the 11p15 imprinted region, was reported in Beckwith-Wiedemann and Silver-Russell syndromes." (PMID 25058480, 2014). "The best characterized imprinted domain is IGF2 that plays a key role in fetal growth, and alterations of methylation are present in fetal growth restriction and in Beckwidth-Wiedemann and Silver-Russell syndromes." (PMID 23840686, 2013). "IGF2 is downregulated through hypomethylation of a differentially methylated region (DMR) in Silver Russell syndrome (SRS), characterised by growth restriction." (PMID 22646060, 2012). "This is in contrast to patients with Beckwith-Wiedemann or Silver-Russell syndrome where both the H19-ICR and IGF2-DMR display a gain or loss of methylation, respectively." (PMID 21991322, 2011). "Our results are consistent with the idea that reduced expression of IGF2 plays a role in the aetiology of the human imprinting-related growth-deficit disorder, Silver-Russell syndrome." (PMID 20062522, 2010). "Dysregulation of the imprinted H19/IGF2 locus can lead to Silver-Russell syndrome (SRS) in humans." (PMID 36441651, 2022). "IGF2 genetic defects and clinical features of patients with Silver-Russell syndrome." (PMID 31803239, 2019). "Russell Silver Syndrome is usually associated with hypomethylation of the ICR, which may lead to a tissue specific loss of IGF2 gene activity and increased activity of the H19 gene." (PMID 23148549, 2012). "Silver-Russell syndrome (SRS), mainly driven by IGF2 / H19 imprinting domain hypomethylation in the 11p15 region, is characterized by IUGR and short stature due to catch-up growth failure." (PMID 38763958, 2024). "In humans, reduced IGF2 expression contributes to the fetal growth restriction in patients with Silver-Russell syndrome (SRS)." (PMID 34963058, 2022). "The clinical importance of the IGF-2 function was acknowledged from the study of patients with the Silver-Russell syndrome (SRS)." (PMID 31939486, 2019). "TS14 is a rare type of growth retardation, the clinical signs of which overlap considerably with those of Silver-Russell syndrome (SRS), another ID related to IGF2 down-regulation at 11p15.5 region." (PMID 30801013, 2019). "Silver-Russell syndrome (SRS) (OMIM #180860), another infrequent imprinting disorder, results from a microdeletion in the chromosomal 11p15.5 region, maternal uniparental disomy (mUPD) of chromosome 7, mutations in the maternally imprinted IGF-2 gene, or other rare molecular abnormalities." (PMID 40413507, 2025). "Analyses in Silver-Russell-syndrome (SRS, a short stature syndrome) patients, that have causative opposing molecular alterations to the BWSp, suggest that IGF-2 serum levels during childhood are unlikely to reflect the methylation status at the IGF2 locus." (PMID 38894719, 2024). "Interestingly, Russell Silver syndrome patients, who have decreased expression of IGF2, have a striking lack of subcutaneous fat as part of their generalized growth retardation." (PMID 23148549, 2012).